OTUB2 (OTU deubiquitinase, ubiquitin aldehyde binding 2)
Description:
Hydrolase that can remove conjugated ubiquitin from proteins in vitro and may therefore play an important regulatory role at the level of protein turnover by preventing degradation. Mediates deubiquitination of 'Lys-11'-,'Lys-48'- and 'Lys-63'-linked polyubiquitin chains, with a preference for 'Lys-63'-linked polyubiquitin chains.
Synonyms: C14orf137; OTB2; OTU2; FLJ21916; MGC3102
Tractability: Small molecule: a structure with a bound ligand is known. PROTAC: ubiquitination databases record sites on it; its protein half-life has been measured.
Target class: Enzyme; Hydrolase
Gene: Protein-coding gene on chromosome 14 (94,026,340 to 94,048,930, forward strand). Ensembl gene ENSG00000089723.
Pathways (Reactome):
Metabolism of proteins: Ovarian tumor domain proteases
Gene Ontology:
Molecular function: cysteine-type deubiquitinase activity; protein binding; ubiquitin binding; hydrolase activity
Biological process: protein deubiquitination; protein K11-linked deubiquitination; protein K48-linked deubiquitination; protein K63-linked deubiquitination
Cellular component: nucleus
Genetic constraint (gnomAD): Loss-of-function variants: 14 observed, 21.14 expected, observed/expected ratio (o/e) 0.66, 90% interval 0.44 to 1.03. The upper end of that interval is the gene's LOEUF score, 1.03, which puts it in group 4 of 6, group 1 being the genes least tolerant of losing a copy. Missense variants: 245 observed, 270.31 expected, observed/expected ratio (o/e) 0.91, 90% interval 0.82 to 1.01. Synonymous variants: 112 observed, 115.02 expected, observed/expected ratio (o/e) 0.97, 90% interval 0.83 to 1.14.
Homologues: Orthologues: chimpanzee OTUB2 (99% identical), macaque OTUB2 (99% identical), dog OTUB2 (95% identical), pig OTUB2 (95% identical), guinea pig OTUB2 (94% identical), mouse Otub2 (94% identical), rat Otub2 (94% identical), rabbit OTUB2 (71% identical), tropical clawed frog otub2 (50% identical), Drosophila melanogaster CG4968 (36% identical), Caenorhabditis elegans otub-1 (28% identical). Paralogues in human: OTUB1 (46% identical).
Diseases named in the same sentence as OTUB2 in open-access papers:
OTUB2 is named in the same sentence as 45 diseases in open-access papers, as found by Europe PMC text mining. Sharing a sentence is not in itself a finding about the gene and the disease. The quoted sentences say what the papers report.
breast carcinoma (14 papers, 2021 to 2026). "Addressing these limitations in future studies will provide a more comprehensive understanding of OTUB2’s function in breast cancer and its potential as a therapeutic target." (PMID 40296903, 2025). "We performed in vitro experimental assays to evaluate the role of OTUB2 in breast cancer progression." (PMID 39115875, 2024). "As for breast cancer, a recent study reported that OTUB2 deubiquitinated and activated YAP/TAZ to promote cancer stemness and metastasis, which confirms the reliability of our results." (PMID 36685836, 2022). "Some researchers have found that OTUB2 promotes the development of breast cancer, non-small cell lung cancer, thyroid papilloma cancer, endometrial cancer, and liver cancer." (PMID 35850645, 2022). "Accordingly, via these mechanisms, OTUB2 facilitates the metastasis of MCF10A-RAS breast cancer cells." (PMID 35110531, 2022). "Existing studies have dedicated less effort on investigating mechanisms associated with OTUB2, YAP1 and TAZ in ESCC, and studies have shown that in breast cancer,OTUB2 can stabilize and activate YAP1/TAZ." (PMID 35850645, 2022). "Given the molecular heterogeneity of breast cancer, it remains unclear whether OTUB2 exerts similar oncogenic effects in hormone receptor-positive or HER2-positive breast cancer." (PMID 40296903, 2025). "In vitro experiments verified that knockdown of OTUB2 could inhibit the proliferation and migration of breast cancer." (PMID 39115875, 2024). "However, in a study of breast cancer, OTUB2 promoted metastasis through hippocampal-independent activation of YAP and TAZ." (PMID 37573347, 2023). "Finally, the function of OTUB2 was explored in breast cancer cells." (PMID 39115875, 2024). "METHODS: We utilized The Cancer Genome Atlas (TCGA) dataset to analyze the expressions of OTUB2, EIF4A3, and TPI1 in breast cancer tissues and specifically in triple-negative breast cancer (TNBC) tissues." (PMID 41857621, 2026). "RESULTS: TCGA database indicated highly expressions of OTUB2, EIF4A3, and TPI1 in breast cancer tissues and TNBC tissues." (PMID 41857621, 2026). "Recent reports have documented that TAZ can be directly deubiquitinated and stabilized by USP1, USP10, OTUB2 and JOSD2 in hepatocellular carcinoma, breast cancer and cholangiocarcinoma." (PMID 35931679, 2022). "Respectively, USP10 and OTUB2 were recently reported as the candidate proteins that deubiquitinated and stabilized YAP/TAZ in the liver and breast cancer models." (PMID 36470870, 2022). "Indeed, USP10 and OTUB2 were recently reported as the candidate proteins that deubiquitinated and stabilized YAP/TAZ in the liver and breast cancer models, respectively." (PMID 35906484, 2023). "However, we primarily focused on the role of OTUB2 in TNBC without investigating its expression and functional significance in other breast cancer subtypes." (PMID 40296903, 2025).
colorectal cancer (10 papers, 2022 to 2026). A primary or metastatic malignant neoplasm that affects the colon or rectum. "One study suggests that deubiquitinase OTUB2 exacerbates colorectal cancer growth by increasing PKM2 activity and glycolysis." (PMID 36681855, 2023). "OBJECTIVE: This study aimed to clarify how cancer-associated fibroblast-derived exosomal circ_0067557 (CAF-exo circ_0067557) promotes epithelial-mesenchymal transition (EMT) in colorectal cancer (CRC) through BHLHE40-mediated transcriptional activation of OTUB2." (PMID 42115880, 2026). "A previous study showed that OTUB2 negatively regulates PKM2 ubiquitination in colorectal cancer." (PMID 39776804, 2025). "OTUB2 was reported to promote the progression of gastric cancer and colorectal cancer." (PMID 36685836, 2022). "For example, it was recently reported that OTUB2 could boost the activity of PKM2, a key enzyme for glycolysis, through protein deubiquitination, thus promoting glycolysis of colorectal cancer and tumor progression." (PMID 40518543, 2025). "In addition, the DUB OTU domain-containing ubiquitin aldehyde-binding protein 2 (OTUB2) interacts with PKM2 to inhibit PKM2 ubiquitination by the E3 ligase Parkin, enhancing glycolysis and accelerating colorectal cancer progression." (PMID 39048965, 2024). "For example, OTUB2 inhibits PKM2 ubiquitination and enhances its activity in colorectal cancer." (PMID 37624791, 2023).
gastric cancer (9 papers, 2022 to 2026). A primary or metastatic malignant neoplasm involving the stomach. "In this research, we discovered that OTUB2 expression was upregulated in gastric cancer and was significantly associated with the poor prognosis of patients." (PMID 35110531, 2022). "Following that, we will focus on the association between OTUB2 and metastasis in gastric cancer through knockout mice developing metastasis model." (PMID 35110531, 2022). "Taken together, both OTUB2 and KRT80 positively promote growth and proliferation in gastric cancer cells in vitro, and OTUB2 also specifically regulates the expression of KRT80 proteins." (PMID 35110531, 2022). "The results indicate that OTUB2 promotes the growth and proliferation of gastric cancer cells in vivo by specifically deubiquitinating the stability of KRT80." (PMID 35110531, 2022). "We believe that OTUB2 will become a novel marker for gastric cancer." (PMID 35110531, 2022). "Nevertheless, we have not yet discussed the association between OTUB2 and gastric cancer metastasis." (PMID 35110531, 2022). "Studies have reported that OTUB2 facilitates cancer metastasis via activating YAP and TAZ and enhances the proliferation of gastric cancer cells by deubiquitinating KRT80." (PMID 40296903, 2025). "Additional studies have suggested that OTUB2 stabilizes KRT80 by deubiquitinating it, consequently promoting gastric cancer progression." (PMID 38495507, 2024). "We constructed a subcutaneous xenograft model to examine the effects of OTUB2 and KRT80 on the proliferation and tumorigenesis of gastric cancer cells in vivo." (PMID 35110531, 2022). "Then we developed OTUB2-knockdown AGS and KRT80-knockdown AGS cells and KRT80-overexpression MKN45 to investigate OTUB2 and KRT80 in gastric cancer with the aid of lentivirus technology." (PMID 35110531, 2022). "However, the expression of OTUB2 and its prognostic importance in gastric cancer remain unclear." (PMID 35110531, 2022). "We then conducted cell proliferation experiments in vitro and discovered that both OTUB2 and KRT80 can promote the proliferation of gastric cancer cells." (PMID 35110531, 2022). "To investigate the function of OTUB2 and KRT80 in gastric cancer cells, we conducted a western blotting analysis of four gastric cancer cell lines first." (PMID 35110531, 2022). "OTUB2 regulates KRT80 stability via deubiquitination and promotes gastric cancer growth." (PMID 39605891, 2024). "Moreover, the interaction between PRKDC and KRT80 protein accelerated invasion in colon cancer 9, and OTUB2 influenced KRT80 stability through deubiquitination, promoting the malignancy of gastric cancer." (PMID 38495507, 2024). "Given that OTUB2 promotes gastric cancer growth and proliferation by positively regulating the activation of the PI3K/AKT signaling pathway via KRT80, we believe that KRT80 also has clinical effects similar to OTUB2." (PMID 37211956, 2023). "Moreover, when OTUB2 expression was decreased, KRT80 protein expression was decreased, inhibiting gastric cancer cells' growth capacity." (PMID 35110531, 2022). "Therefore, while the data do not support a positive impact of OTUB2 on gastric cancer metastasis, we cannot rule it out entirely." (PMID 35110531, 2022). "We then investigated the relationship between the two and discovered that OTUB2 was indeed capable of stabilizing KRT80 by specifically deubiquitinating it via Lys-48 and Lys-63, thereby activating the Akt pathway and thus promoting gastric cancer cell proliferation." (PMID 35110531, 2022).
gastric cancer (continued). "Multiple immunofluorescence (IF) staining analysis was performed to evaluate OTUB2 and KRT80 expression in a tissue microarray (TMA) consisting of 90 cases of primary gastric cancer with different tumor differentiation and paired adjacent normal tissues." (PMID 35110531, 2022). "And the expression of OTUB2 and KRT80 proteins was not 100% consistent in gastric cancer and paired adjacent normal tissues." (PMID 35110531, 2022).
ovarian tumor (8 papers, 2022 to 2025). "OTUB2, a member of the ovarian tumor-like proteases family, has been implicated in non-small cell lung cancer tumorigenesis and prognosis." (PMID 35110531, 2022). "OTUB2, or otubain 2, is a deubiquitinase, a member of the protein superfamily of ovarian tumor (OTU) was identified as a Drosophila ovary tumor gene for the first time." (PMID 35850645, 2022). "Ovarian tumor (OTU) domain-containing ubiquitin aldehyde-binding protein Otubain2 (OTUB2) was a functional cysteine protease in the OTU family with deubiquitinase activity." (PMID 35309903, 2022). "OTUB2 is a deubiquitinase of the ovarian tumor protease family." (PMID 41338459, 2025). "Like A20 and OTUD1, otubain 2 (OTUB2) is a DUB of the ovarian tumour protease subfamily." (PMID 39358938, 2024). "Thus, Pearson correlation analysis between the expression level of B4GALT5 and OTU (ovarian tumour) family deubiquitinases (OTUB1, OTUB2, OTUD1, YOD1, OTUD3, OTUD4, OTUD7B) was performed." (PMID 36611197, 2023).
non-small cell lung carcinoma (6 papers, 2022 to 2025). A group of at least three distinct histological types of lung cancer, including non-small cell squamous cell carcinoma, adenocarcinoma, and large cell carcinoma. "To underscore relevance in human patients, we observe a significant correlation between OTUB2 expression and PD-L1 abundance in human non-small cell lung cancer." (PMID 38167274, 2024). "The study first observed that in non-small cell lung cancer, the overexpression of OTUB2 protein promoted the Warburg effect (enhanced cellular glycolysis)." (PMID 35309903, 2022). "OTUB2 is linked to the Akt/mTOR pathway by targeting U2AF2, unfortunately, the molecular mechanism of U2AF2 in non-small cell lung cancer is still unclear." (PMID 35309903, 2022). "One of these genes (OTUB2) promotes tumorigenesis in non-small cell lung cancer through pathways involving the Warburg effect." (PMID 35163690, 2022). "Additionally, OTUB2 plays a pivotal role in the tumorigenesis of non-small cell lung cancer via the stabilization of U2AF2 and activation of the AKT/mTOR pathway." (PMID 35110531, 2022). "Similarly, in non-small cell lung cancer, OTUB2 could bind to U2AF2 and deubiquitinate it, making U2AF2 more stable, promoting the Warburg effect of tumors through the AKT/mTOR signaling pathway." (PMID 38819228, 2024).
colon cancer (4 papers, 2013 to 2024). "To explore the potential role of OTUB2 in intestinal inflammation, we first compared the expression of OTUB2 in normal adjacent colon tissues from colon cancer patients and inflamed colon samples from UC patients." (PMID 39358938, 2024). "Additionally, we were able to identify other genes highly upregulated in tumor samples, including ABHD7, TMPRSS3 or OTUB2, which had not been previously associated with this pathology, and might constitute novel candidate genes for colon cancer." (PMID 24243807, 2013).
esophageal squamous cell carcinoma (4 papers, 2022 to 2025). Esophageal squamous cell carcinoma (ESCC) is a type of esophageal carcinoma (EC) that can affect any part of the esophagus, but is usually located in the upper or middle third. "A study published in Cell Reports revealed the important antitumor function of the deubiquitinating enzyme OTUB2 in oral and esophageal squamous cell carcinomas by promoting phosphorylation and dimer formation of the transcription factor STAT1." (PMID 37573347, 2023). "To observe the effects of OTUB2 knockdown on the proliferation, migration, and invasion of esophageal squamous cell carcinoma cells, we carried out cell function experiments." (PMID 35850645, 2022). "Western blotting was used to detect the expression of OTUB2 protein in three esophageal squamous cell carcinoma cell lines, and the cell line with the highest expression of OTUB2 was selected for lentiviral transfection to knockdown OTUB2 expression." (PMID 35850645, 2022). "OTUB1 and OTUB2 potentiated esophageal squamous cell carcinoma (ESCC) proliferation and metastasis by regulating the stability of Snail and YAP1/TAZ proteins, respectively." (PMID 40469292, 2025). "The effects of Otubain-2 (OTUB2) on the proliferation, invasion, and migration of esophageal squamous cell carcinoma (ESCC) were investigated by interfering with OTUB2 expression." (PMID 35850645, 2022). "Immunofluorescence was used to detect the expression of OTUB2 in the normal esophageal epithelial cell line SHEE and the esophageal squamous cell carcinoma cell line KYSE150." (PMID 35850645, 2022).
liver fibrosis (3 papers, 2022 to 2025). "Additionally, a previous study that explored other pathways leading liver fibrosis found that pantoprazole was significantly fibrogenic, both in vitro and in vivo, by inhibiting the deubiquitinating enzyme OTUB2 and the Yes-associated protein signaling pathway." (PMID 40649803, 2025). "PPZ also disrupted the interaction between the deubiquitinating enzyme OTUB2 and YAP, leading to YAP destabilization and impeding hepatic fibrosis progression." (PMID 39479501, 2024). "Not limited to cancer, the latest research has shown that pantoprazole promotes the degradation of YAP and finally blocks the progress of liver fibrosis by breaking the interaction between OTUB2 and YAP, which indirectly demonstrates that OTUB2 contributes to the progression of liver fibrosis." (PMID 35309903, 2022).
cervical cancer (2 papers, 2024). A primary or metastatic malignant neoplasm involving the cervix. "Similarly, in cervical cancer, RBM15 inhibition reduces m6A methylation of OTUB2, leading to the inactivation of the AKT/mTOR pathway, which in turn decreases cell proliferation and metastasis capacity." (PMID 39716068, 2024). "In addition, RBM15-mediated m6A modification facilitated the expression of the oncogene Otubain 2 (OTUB2) in cervical cancer cells, which further activated AKT/mTOR signaling, thereby promoting the proliferation, migration, and invasion of cervical cancer cells." (PMID 38915367, 2024).
endometrial cancer (2 papers, 2022 to 2025). Primary or metastatic malignant neoplasm involving the endometrium (mucous membrane that lines the endometrial cavity). "OTUB2 contributed to endometrial cancer (EC) progression by regulating the PKM2-mediated PI3K/AKT signaling pathway." (PMID 40469292, 2025). "In endometrial cancer, OTUB2 promoted Rad51 expression via the YAP/TAZ pathway, supporting homologous recombination repair and protecting cells from drugs like cisplatin." (PMID 40469292, 2025). "Silencing of OTUB2 can inhibit the growth of endometrial cancer and increases the sensitivity of tumor to anti-tumor drugs." (PMID 35850645, 2022). "It has also been reported that OTUB2 promotes homologous recombination repair of endometrial carcinoma through YAP/TAZ mediated Rad51 expression, which provides a potential therapeutic target for endometrial carcinoma." (PMID 35850645, 2022).
liver cancer (2 papers, 2022). An epithelial or non-epithelial malignant neoplasm that arises from the liver. "In the HCC cell line, knocking-down OTUB2 expression can significantly inhibit the growth of liver cancer cells." (PMID 35850645, 2022). "In liver cancer, the knockout of OTUB2 suppressed the phosphorylated p65 level in liver cancer cells." (PMID 35309903, 2022).
lung carcinoma (2 papers, 2024 to 2025). "We first examined the effect of OTUB2 deficiency on PD-L1 levels on the surface of lung cancer cells." (PMID 38167274, 2024). "To determine whether OTUB2 affects PD-L1 degradation through the proteasome, we examined the effect of MG132 or the lysosomal inhibitor chloroquine on the PD-L1 levels in OTUB2-KD lung cancer cells." (PMID 38167274, 2024). "In lung cancer, OTUB1 triggered lung cancer development by inhibiting RAS monoubiquitination; OTUB2 stabilized U2AF2 through the AKT/mTOR signaling pathway to promote the Warburg effect and tumorigenesis; and OTUD3 stabilized GRP78 to augment the malignancy." (PMID 40469292, 2025).
triple-negative breast carcinoma (2 papers, 2025 to 2026). An invasive breast carcinoma which is negative for expression of estrogen receptor (ER), progesterone receptor (PR), and human epidermal growth factor receptor 2 (HER2). "Nevertheless, the pathophysiological function of OTUB2 in triple-negative breast cancer remains indistinct." (PMID 40296903, 2025). "Although previous studies have illuminated the role of OTUB2 in tumor progression, its relationship with proliferation and metastasis in triple-negative breast cancer is still unclear." (PMID 40296903, 2025).
amyotrophic lateral sclerosis (1 paper, 2022). Amyotrophic lateral sclerosis (ALS) is a neurodegenerative disease characterized by progressive muscular paralysis reflecting degeneration of motor neurons in the primary motor cortex, corticospinal tracts, brainstem and spinal cord. "For instance, the integration of gene tissue microarrays suggests that OTUB2 is a specifically expressed motor neuron degeneration signal factor in amyotrophic lateral sclerosis." (PMID 35309903, 2022).